BSG (basigin (Ok blood group))
Diseases named in the same sentence as BSG in open-access papers (continued):
Sharing a sentence is not in itself a finding about the gene and the disease.
infection (113 papers, 2014 to 2025). The state of being infected such as from the introduction of a foreign agent such as serum, vaccine, antigenic substance or organism. "Targeting of the known ACE2 receptor by CRISPR-Cas9 led to a near-complete loss of infectivity (two-way ANOVA of ACE2 infection vs B2M control Bonferroni-corrected p-value < 0.001), despite these cells retaining very high expression of BSG." (PMID 33432067, 2021). "Interestingly, we found decreased levels of SARS-CoV-2 mRNA expression in the infected BSG KO kidney organoids compared with WT counterparts, suggesting that BSG deletion might have an impact on the infection susceptibility of the organoids." (PMID 35561674, 2022). "BSG was reported to participate in the cytokine storm via modulation of CyPA expression, and anti-BSG antibody potently reduce the infection and cytokine storm of SARS-CoV-2." (PMID 38484369, 2024). "Meplazumab blocked BSG interaction with S protein and inhibited host cell infection in a dose-dependent manner." (PMID 38484369, 2024). "Specifically, while knockdown of BSG/CD147 or treatment with DPP4 inhibitor (vildagliptin) significantly reduces SARS-CoV-2 infection, conversely overexpressing BSG/CD147 or DPP4 increases infection in vitro." (PMID 35858460, 2022). "Knowledge about the expression of ACE2 and TMPRSS2, as well as other potential entry genes of SARS-CoV-2, namely FURIN, DPP4, and BSG, is extremely important to understand the infection of SARS-CoV-2 and to find ways to prevent the infection." (PMID 33081421, 2020). "Specifically, it is important to further assess susceptibility and permissibility of endothelial cells to SARS-CoV-2 and the role (if any) BSG plays in infection." (PMID 33073064, 2020). "In this case, PPIB forms a complex with the malaria pathogen (Plasmodium falciparum merozoites) and BSG to facilitate infection of red blood cells." (PMID 33073064, 2020). "This is in contrast to other cell types such as endothelial and epithelial cells, whose infection instead depends on the expression of surface molecules (such as BSG), acting as receptors for specific glycoprotein complexes present on the virion’s surface." (PMID 30949159, 2019). "Our findings that endothelial cells remain non-susceptible to infection with SARS-CoV-2 despite expressing high levels of BSG suggest that the BSG pathway is not a functional entry pathway for SARS-CoV-2 in endothelial cells." (PMID 41347787, 2025). "In addition to ACE2 and TMPRSS2, other potential SARS-CoV-2 receptors, proteases and cofactors for infection have been suggested, including BSG (CD147) and neuropilin-1 (NRP1)." (PMID 33380340, 2020). "Furthermore, OM-ALI cells expressed genes for all the characteristic proteins that are important for viral entry and infection, such as TMPRSS-2, CTSB, CTSL, NRP-1, BSG, and furin." (PMID 38098019, 2023). "Besides ACE2, the most prominent receptor, other receptors that mediate CoV2 infection of human cells include neuropilin-1 (NRP1), Eph receptors, transmembrane serine protease 2 (TMPRSS2), P2X7, and CD147 (BSG)." (PMID 38203569, 2023). "We also quantified the relative expression of BSG/CD147, ACE2 (given its involvement in SARS-CoV-2 binding and infection of many cell types), as well as cell surface protease TMPRSS2 and endosomal Cathepsin L (CTSL) in podocytes infected with SARS-CoV-2 for 72 h using different MOIs." (PMID 35517495, 2022). "Consistent with this, we found no functional role for BSG in the infection of a human lung cell line with SARS-CoV-2." (PMID 33432067, 2021). "In addition to ACE2 and TMPRSS2, other potential SARS-CoV-2 receptors, proteases and cofactors for infection have been suggested, including BSG (CD147) and NRP1 as receptors, and CTSL as a key protease." (PMID 32750256, 2020). "Other co-receptors may also be involved in cellular infection, including CD147 (basigin, BSG) and CD2620,22." (PMID 32363596, 2020).
infection (continued). "This is in line with recent reports, suggesting that ACE2 and TMPRSS2 expression might be prerequisite for BSG and NRP1 to exert their infection-potentiating activity Interestingly, previous studies have shown that ACE2 expression is regulated by IFNα and IFNγ signalling." (PMID 35837388, 2022). "We encourage greater study in confirming the mechanisms that have been proposed, not just for BSG but also for the multiple other putative viral receptors, so as to resolve the uncertainty around whether SARS-CoV-2 utilizes any receptors beyond ACE2 during infection." (PMID 33432067, 2021).
cardiovascular diseases (17 papers, 2017 to 2025). "The expression of BSG in endothelial cells has been found to be positively correlated with age in humans, which may explain the increased risk of cardiovascular disease with advancing age." (PMID 34337051, 2021). "Finally, because BSG is implicated in a range of cardiovascular diseases and fibrosis, our observations may have relevance to our understanding of the diseases associated with aging." (PMID 33073064, 2020). "In a wider setting, considering the well-established role of BSG in cardiovascular disease, our results have clear im- plications for our understanding of aging in the cardiovascular system." (PMID 33073064, 2020).
adenocarcinoma (13 papers, 2011 to 2025). A common cancer characterized by the presence of malignant glandular cells. "MCT1, MCT4 and BSG were expressed in 20%, 30% and 40% of the cases of adenocarcinomas, respectively." (PMID 25894929, 2015).
hematologic malignancies (5 papers, 2018 to 2024). "rs8259 was described in three different non-haematologic diseases in which allele T was associated with lower mRNA BSG expression and lower plasma levels of soluble BSG." (PMID 29695106, 2018).
metabolic disease (4 papers, 2014 to 2021). A congenital disorder (due to inherited enzyme abnormality) or acquired (due to failure of a metabolically important organ) disorder resulting from an abnormal metabolic process. "Taken together, the plasma membrane–selective modulation of lactate and pyruvate transport through BSG inhibition could potentiate metabolic flexibility to treat metabolic diseases." (PMID 34676828, 2021).
BSG also shares sentences with these, for which no sentence is quoted: colorectal cancer (42 papers); pancreatic cancer (40); atherosclerosis (38); gastric cancer (37); rheumatoid arthritis (37); lymph node metastasis (24); liver fibrosis (17); oral squamous cell carcinoma (16); Stroke (16); acute myocardial infarction (12); Alzheimer disease (12); pulmonary fibrosis (12); acute myeloid leukemia (11); kidney diseases (11); ischemic stroke (10); metastatic tumors (10); renal carcinoma (10); Cirrhosis (9); coronary artery disease (9); osteosarcoma (9); renal cell carcinoma (9); renal fibrosis (9); ischemia (8); lymphopenia (8); periodontitis (8); pneumonia (8); cardiac ischemia (7); Cerebral ischemia (7); head and neck cancer (7); Hyperglycemia (7).
A further 283 diseases each share a sentence with BSG in 7 papers or fewer.